FXR2 (FMR1 autosomal homolog 2)
Diseases named in the same sentence as FXR2 in open-access papers (continued):
Sharing a sentence is not in itself a finding about the gene and the disease.
cancer (continued). "However, little is known regarding the function of FXR2 in cancer compared to FXR1 and FMRP." (PMID 40149453, 2025). "This suggests that FXR2 may depend on other genes in cancer progression." (PMID 40149453, 2025). "However, studies on the prognostic significance of FXR2 in cancer are scarce." (PMID 40149453, 2025). "Furthermore, some genes (e.g., FXR2, METTL16) generally show copy number losses in pan-cancer, while some (e.g., IGF2BP3, YTHDF1) primarily exhibit copy number amplifications." (PMID 40867324, 2025). "To date, no study has investigated the significance of FXR2 in cancer progression." (PMID 40149453, 2025).
cancer (continued). "As expected the level of FXR1 is highly amplified in cancer tissues compared to normal adjacent tissues and we do not see differential expression of FMR1 and FXR2." (PMID 27606879, 2016).
tumor (6 papers, 2016 to 2025). "Immunohistochemistry (IHC) was used to assess FXR2 protein expression in the BC tissues, and the results were correlated with clinicopathological parameters, such as tumor grade, tumor size and hormone receptor status." (PMID 40149453, 2025). "Although no other significant correlations were found with the remaining clinicopathological parameters, FXR2 can be seen to be overexpressed in tumor sizes ≥ 10 mm (64.3%), in TNM stage IIB (90.9%), and in negative lymph nodal status (64%)." (PMID 40149453, 2025). "FXR1, FXR2 and hnRNPK are required for these treRNA functions, while their expression promotes tumour invasion in vitro and metastasis in vivo." (PMID 34044876, 2021). "Briefly, the combination of hnRNPK and FXR2 affects tumour metastasis in vivo, however, the curative mechanism need to be evaluated." (PMID 34044876, 2021). "FXR1 mRNA levels along with two other FXR1 families of proteins FMR1 and FXR2 were determined in 521 tumor samples." (PMID 27606879, 2016). "This could explain the correlation between FXR2 and TNBC, which could be attributed to the heterogeneity of the tumor cells and the co-expression of certain genes with FXR2." (PMID 40149453, 2025). "This suggests that FXR2 may initially increase to inhibit tumor growth, but it could subsequently lose its suppressive role in later stages, potentially due to its co-expression with other genes." (PMID 40149453, 2025). "Additionally, Qihong Huang identified a novel ribonucleprotein (RNP) complex (hnRNPK, FXR1, FXR2, PUF60, SF3B3), which is required for translational regulation of lncRNA to cause tumor invasion and metastasis." (PMID 34057025, 2021). "FXR1 mRNA is overexpressed in tumor compared to normal adjacent tissues, whereas FMR1 and FXR2 mRNA levels are comparable to their normal mRNA expression." (PMID 27606879, 2016). "However, we did not observe a significant difference in expression for FXR2 in normal adjacent and HNSCC tumor tissues." (PMID 27606879, 2016). "Moreover, knockdown of hnRNPK or FXR1 but not FXR2 increased the tumour growth of mouse model with MCF7 cells, whereas double knockdown or triple knockdown of the RNA-binding proteins significantly decreased primary tumour growth." (PMID 34044876, 2021).
nervous system disorder (3 papers, 2022 to 2024). A non-neoplastic or neoplastic disorder that affects the brain, spinal cord, or peripheral nerves. "Previous studies have shown that Fxr2 is involved in numerous neurological diseases." (PMID 38802919, 2024).
infection (2 papers, 2018 to 2023). The state of being infected such as from the introduction of a foreign agent such as serum, vaccine, antigenic substance or organism. "At 6 days post-infection, protein expression levels of FXR2 and PNPLA6 [a validated FMRP target] were measured in testes." (PMID 30511641, 2018). "At 24 hr post-infection, cells were harvested and analyzed for FXR2 expression." (PMID 30511641, 2018). "Measurements of viral genomes indicated a higher burden of infection for the WT virus than Δ10 ZIKV which may contribute to the differential effects on FXR2 and PNPLA6 levels." (PMID 30511641, 2018). "Interestingly, infection with Δ10 ZIKV, but not WT ZIKV, caused relocalization of FXR2 to cytoplasmic granular structures reminiscent of stress granules (SG), suggesting that sfRNA may prevent SG formation." (PMID 30511641, 2018).
FXR2 also shares sentences with these, for which no sentence is quoted: neurodegenerative disease (2 papers); cervical cancer (1); depression (1); endometriosis (1); epilepsy (1); Huntington disease (1); stomach adenocarcinoma (1).